TIGAR (TP53 induced glycolysis regulatory phosphatase)
Diseases named in the same sentence as TIGAR in open-access papers (continued):
Sharing a sentence is not in itself a finding about the gene and the disease.
lung carcinoma (15 papers, 2013 to 2025). "TIGAR is overexpressed in many types of cancers, including leukemia, lung cancer, colon cancer, and liver cancer." (PMID 40277923, 2025). "The relationship between TIGAR and various solid tumors, including primary colon carcinoma, invasive breast carcinoma, lung cancer, nasopharyngeal carcinoma, gastric cancer, renal cell carcinoma, and prostate carcinoma, has been studied." (PMID 39091612, 2024). "Chen et al37 suggested that miR‐144 inhibits lung cancer cell proliferation and induces cell apoptosis and autophagy by targeting TIGAR." (PMID 32965722, 2021). "Previous studies have suggested that depletion of TIGAR results in a decrease in MET expression in lung cancer cell lines, but we were unable to detect any difference in MET expression in our PDAC cells." (PMID 31983610, 2020). "Immunohistochemical analysis of 72 NSCLC patients showed that TIGAR and Met protein expression was positively correlated with late stages of lung cancer." (PMID 29753331, 2018). "To explore the role of TIGAR in lung cancer invasion and metastasis, we investigated the endogenous levels of TIGAR in five human NSCLC cell lines." (PMID 29753331, 2018). "We have proposed to conduct a trial of a TIGAR activator for the treatment of lung cancer in PET-positive mice with the aim of developing potential gene targeted therapies for lung cancer." (PMID 24363807, 2013). "Taken together, our findings reveal that the TIGAR may serve as a potential therapeutic target to increase the sensitivity of lung cancer A549 cells to cisplatin." (PMID 36555672, 2022). "Finally, hsa-mir-144 impacts the patient survival at the fourth stage of LUAD, which regulates EZH2, TIGAR, Lico A, etc. that affect lung cancer." (PMID 32428028, 2020). "Then we investigate whether TIGAR also affects lung cancer metastasis in vivo." (PMID 29753331, 2018). "We observed significant elevation of cellular TIGAR levels by MARS2 knockdown in A549 and H460 lung cancer cells." (PMID 36774778, 2023). "In order to understand the role of TIGAR and its potential use as a biomarker in NSCLC, an immunohistochemical analysis of 72 NSCLC patients was conducted, and it showed that both TIGAR and Met expression correlated positively with late stages of lung cancer." (PMID 40277923, 2025).
glioblastoma (11 papers, 2014 to 2025). The most malignant astrocytic tumor (WHO grade IV). "More confusing is the association of TIGAR with senescence, where loss of TIGAR can induce senescence in glioblastoma cells but can also inhibit this process in adult T-cell leukaemia cells." (PMID 24383451, 2014). "An upregulation of TIGAR was observed in glioblastoma associated with poor survival." (PMID 40277923, 2025). "TIGAR overexpression in patients was inversely correlated with the survival time of patients with glioblastoma." (PMID 40277923, 2025). "It has been shown that TIGAR is overexpressed in glioblastoma patients’ tissues as well as in the glioblastoma cell line U-87MG." (PMID 40277923, 2025). "TIGAR overexpressed in glioblastoma, and ectopic expression of TIGAR reduced cell death induced by glucose and oxygen restriction." (PMID 36437984, 2022). "Glioblastoma cells overexpress TIGAR which reduces cell death induced by restricting glucose and oxygen." (PMID 30234009, 2018). "The results correspond with those from recent studies in which TIGAR was revealed to be involved in the tumorigenesis of intestinal cancer and glioblastomas." (PMID 25621025, 2015). "TIGAR can be considered as a potential target for treating glioblastoma." (PMID 40277923, 2025). "It would be interesting to analyze whether NRF2 inhibition is also beneficial for those cancer types in which TIGAR abrogation has been shown to increase sensibility to radio- and chemotherapy, the case, for example, of glioblastoma." (PMID 35163828, 2022). "Moreover, TIGAR silencing has been shown to increase sensitivity of glioblastoma cells to radiotherapy and increase cell death mediated by PFKFB3 inhibition." (PMID 30234009, 2018). "In glioblastoma-derived cell lines, TIGAR abrogation increased radiation-induced cell destruction, providing a new therapeutic strategy that could be used to increase cell death in glial tumors, thus allowing the use of lower doses of radiotherapy." (PMID 30234009, 2018). "In addition, knockdown of TIGAR gene increased Fru-2,6-P2 and reactive oxygen species (ROS) levels and decreased GSH levels in glioblastoma cells." (PMID 27884166, 2016). "Upon TIGAR knockdown and TMZ treatment, anti-apoptotic bcl-2 protein was decreased with an increase in bax pro-apoptotic protein, implying the increase in apoptosis in these cells in addition to having a significant effect on migration and invasion of glioblastoma cells." (PMID 40277923, 2025).
colon carcinoma (9 papers, 2016 to 2024). "In another study using a TIGAR deficient mouse model, decreased TIGAR expression reduced colon tumor burden and size, resulting in a better survival outcome." (PMID 31892967, 2020). "The effectiveness of GO-203 in colorectal tumor xenografts can be linked to MUC1 and TIGAR expression in human colon cancers." (PMID 28153010, 2017). "The previous study had reported inhibition of MUC1‐C in hematological malignancies and colon cancer downregulates TIGAR at the protein level." (PMID 30523643, 2019). "Targeting MUC1‐C has been reported to inhibit TIGAR at the protein level in hematologic malignancies (Yin, Kosugi, & Kufe, 2012; Yin, Kufe, Avigan, & Kufe, 2014) and colon cancer." (PMID 30523643, 2019). "TIGAR protein has been reported to be overexpressed in colon cancer." (PMID 28153010, 2017). "Indeed, TIGAR has been reported to be highly expressed in human colon cancers with a tumorigenic phenotype." (PMID 28153010, 2017). "Our results showed that IC261 could decrease the protein expression of TIGAR and increase the protein expression of G6PD in colon cancer cells." (PMID 32071557, 2020). "Moreover, MUC1-C could block the eIF4A cap-dependent translation of TIGAR, and GO-203 could induce the suppression of TIGAR by inhibiting the MUC1-AKT-mTOR-S6K1-eIF4A pathway, further inhibiting the growth of colon cancer cells." (PMID 35154471, 2022).
pancreatic cancer (9 papers, 2020 to 2025). "TIGAR deficiency, which leads to more ROS, increases metastasis in a mouse model of pancreatic cancer, and we show here that overexpression of TIGAR (resulting in less ROS) decreases tumor invasiveness." (PMID 39636862, 2024). "In line with this, TIGAR expression is SMAD dependent while SMAD4 deficiency is commonly observed in a later stage of pancreatic cancer." (PMID 33941245, 2021). "TIGAR deficiency, which leads to more ROS, increases metastasis in a mouse model of pancreatic cancer, and overexpression of TIGAR (resulting in less ROS) decreases tumor invasiveness." (PMID 40277923, 2025). "Each model was crossed with a Tigarfl/fl strain to generate pancreatic tumors that retained TIGAR expression (CTR) or deleted (KO) for TIGAR." (PMID 40277923, 2025). "Overexpression of TIGAR in metastatic pancreatic tumors therefore served to limit ROS, migration, and metastasis to the lung, consistent with the phenotypes observed in TIGAR null PDAC." (PMID 39636862, 2024). "In support of this idea, a study of pancreatic cancer demonstrated a differential regulation of tumor initiation versus metastatic progression by TIGAR, an antioxidant gene." (PMID 35193955, 2022). "It has been recently described that TIGAR is required for pancreatic cancer cells in tumour initiation and development of established metastases." (PMID 34299056, 2021). "In this study high levels of TIGAR first promote pancreatic cancer initiation by limiting ROS, thereafter low levels of TIGAR promote the metastatic capacity of pancreatic cancer cells by enhancing ROS." (PMID 33909153, 2021). ") Taken together, our data indicate that increased oxidative stress due to loss of TIGAR in KFC and KPC pancreas cancer models delays initial tumor development but enhances metastatic progression at later stages." (PMID 31983610, 2020). "For instance, in pancreatic cancer, TIGAR supports premalignant tumor initiation." (PMID 40277923, 2025). "These tumor models were then used to study the effects of TIGAR on pancreatic cancer." (PMID 40277923, 2025). "Although TIGAR is normally expressed in almost all tissues like muscle, brain, and heart, on the other hand, it is also highly expressed in Alzheimer’s and some types of tumors such as colon, breast, and pancreatic cancer." (PMID 40277923, 2025). "In this study, we examine the role of TIGAR in the development of pancreatic cancer." (PMID 31983610, 2020).
colorectal cancer (8 papers, 2017 to 2025). A primary or metastatic malignant neoplasm that affects the colon or rectum. "In any case, in a pancreatic ductal adenocarcinoma model, loss of TIGAR did not improve survival, and even amplified metastatic spread, and in colorectal cancer patients, a higher TIGAR plasma level was associated with lower risk of metastasis." (PMID 30823646, 2019). "Some of these studies have pointed out the involvement of TIGAR in different stages of disease progression, such as colorectal cancer." (PMID 34299056, 2021). "TIGAR drives colorectal cancer ferroptosis resistance through the ROS–AMPK–SCD1 pathway." (PMID 37238692, 2023). "Hence, inhibition of MUC1-C blocks the cellular proliferation and survival of colorectal cancer cells leading to tumor regression in colorectal xenografts models and inhibits TIGAR expression in xenograft tissues." (PMID 28153010, 2017). "GO-203 treatment of colorectal cancer cells also resulted in the depletion of TIGAR protein without any change in mRNA levels." (PMID 28153010, 2017). "Specifically, TIGAR contributes to ferroptosis resistance in colorectal cancer via the ROS/AMPK/SCD1 axis, while aspirin enhances RSL3-driven ferroptosis by inhibiting mTOR/SREBP-1 (sterol regulatory element-binding protein-1)/SCD1-regulated lipogenesis in PIK3CA-mutant colorectal cancer." (PMID 39935430, 2025).
leukemia (7 papers, 2016 to 2025). A malignant (clonal) hematologic disorder, involving hematopoietic stem cells and characterized by the presence of primitive or atypical myeloid or lymphoid cells in the bone marrow and the blood. "Our results also showed that glycolysis inhibition or TIGAR knockdown alone only caused the limited apoptosis of leukemia cells." (PMID 27884166, 2016). "In the present study, it was found that TIGAR (an important regulator of oxidative stress) is the target of DAC-induced ROS production to mediate leukemia cell apoptosis." (PMID 33532040, 2021). "In contrast, a robust leukemia cell apoptosis was observed when leukemia cells with simultaneous impairment of TIGAR expression and glycolysis." (PMID 27884166, 2016). "The combination of 2-DG and TIGAR knockdown significantly increased the leukemia cell apoptosis in comparison with either 2-DG or TIGAR knockdown." (PMID 27884166, 2016). "We showed that TIGAR knockdown further enhanced the percentage of cell death/necrosis in 2-DG-treated leukemia cells." (PMID 27884166, 2016). "Knockdown of TIGAR inhibited the proliferation of human leukemia cells and sensitized leukemia cells to glycolysis inhibitor both in vitro and in vivo." (PMID 27884166, 2016). "Knockdown of TIGAR significantly increased leukemia cell apoptosis in both HL-60 and NB-4 cell lines, indicating a potential anti-apoptotic effect of TIGAR." (PMID 27884166, 2016). "TIGAR also showed high expression in multiple human leukemia cell lines and knockdown of TIGAR activated glycolysis through PFKFB3 upregulation in human leukemia cells." (PMID 27884166, 2016). "In the future, it will be important to understand how TIGAR affects the response of leukemia cells to chemotherapy or targeted therapy." (PMID 27884166, 2016). "Knockdown of TIGAR inhibited the proliferation of human leukemia cells and sensitized leukemia cells to glycolysis inhibitor 2-DG both in vitro and in vivo." (PMID 27884166, 2016). "TIGAR shRNA constructs by targeting distinct TIGAR sequence was stably introduced into two different leukemia cell lines: HL-60 and NB-4." (PMID 27884166, 2016). "As expected, the combination of 2-DG and TIGAR knockdown significantly increased the leukemia cell apoptosis." (PMID 27884166, 2016). "TIGAR knockdown and 2-DG combination also significantly reduced leukemia cells in the spleens from HL-60 cells xenograft mice." (PMID 27884166, 2016). "Knockdown of TIGAR induced while overexpression of TIGAR reduced the expression of glycolysis activator PFKB3 in leukemia cells." (PMID 27884166, 2016). "Considering the dual regulatory effects of TIGAR on apoptosis and autophagy, TIGAR may be one of the drug targets for the clinical treatment of leukemia." (PMID 33532040, 2021). "Our findings suggest that combining glycolytic inhibitors with a potential TIGAR inhibitor and current standard chemotherapy may be a powerful and effective treatment for not only human leukemia but also other cancer types." (PMID 27884166, 2016).